HOXA10 (homeobox A10)
Diseases named in the same sentence as HOXA10 in open-access papers (continued):
Sharing a sentence is not in itself a finding about the gene and the disease.
polycystic ovary syndrome (6 papers, 2020 to 2025). A disorder that manifests as multiple cysts on the ovaries. "It is reported that the expression of HOXA10 in patients with polycystic ovary is positively correlated with the concentrations of blood HDL and is negatively correlated with the concentrations of blood TG, TC, and LDL." (PMID 35546998, 2022). "Additionally, HOXA10 also has a strong correlation with serum lipid in polycystic ovary syndrome." (PMID 35546998, 2022).
liver cancer (5 papers, 2015 to 2025). An epithelial or non-epithelial malignant neoplasm that arises from the liver. "To further study the mechanism of SHP-1 inhibition of liver cancer, we analyzed the expression of p-HOXA10/TGFβ2 in macrophage and the migration ability of SMMC7721 cells under the interference of GM-CSF and hypoxia." (PMID 38644382, 2024). "Here, we examined the expression pattern of HOX transcription factors, and found HOXA10 was overexpressed in liver cancer samples." (PMID 30545354, 2018). "We then collected primary cells and examined the expression levels of HOXA10 with realtime PCR, immunohistochemistry and Western blot, confirming the high expression of HOXA10 in liver cancer." (PMID 30545354, 2018). "Through unbiased screening, here we examined the expression profile of HOX TFs in liver cancer, and found HOXA10 (homeobox A10) was the most highly expressed HOX transcription factor in liver tumor." (PMID 30545354, 2018). "Likewise, the long non-coding RNA lncHOXA10 interacts with SNF2L and recruits the NURF chromatin remodeling complex to the HOXA10 promoter in liver cancer TICs, contributing to HOXA10 expression and liver cancer progression." (PMID 40568600, 2025). "In addition, GM-CSF also promoted the expression of p-HOXA10 and TGFβ2 in liver cancer cells and inhibited the inhibitory effect of SHP-1." (PMID 38644382, 2024). "Altogether, HOXA10 was up-regulated in liver cancer and liver TICs." (PMID 30545354, 2018). "HOXA10 was the most highly expressed HOX transcription factor in liver cancer and liver TICs." (PMID 30545354, 2018). "Moreover, a divergent lncRNA of HOXA10 (termed lncHOXA10 hereafter) was also highly expressed in liver cancer and liver TICs." (PMID 30545354, 2018). "Of the denoted HOX TFs, HOXA10 was the highest expressed HOX transcription factor in liver cancer." (PMID 30545354, 2018). "Here we found lncHOXA10 is co-expressed with HOXA10 in liver cancer and liver TICs." (PMID 30545354, 2018). "Here, we found lncHOXA10 and HOXA10 are highly expressed in liver cancer and liver TICs." (PMID 30545354, 2018). "Moreover, HOXA10 expression levels were also related to clinical severity of liver cancer." (PMID 30545354, 2018). "Here, we demonstrated that hypoxia and GM-CSF synergistically promoted M2 polarization and migration and proliferation of liver cancer through the inhibition of SHP-1 and SHP-2 phosphorylation and the increase of p-HOXA10 expression." (PMID 38644382, 2024). "Previous research has demonstrated that HOXA10 can promote cancer cell proliferation by directly binding to the HDAC1 promoter and upregulating HDAC1 expression in liver cancer cells." (PMID 33596966, 2021).
myeloid leukemia (5 papers, 2017 to 2022). A clonal proliferation of myeloid cells and their precursors in the bone marrow, peripheral blood, and spleen. "The identification of HoxA10 protein phosphorylation modifications has mainly focused on myeloid leukemia cells thus far, and these modifications are even less studied in the uterus." (PMID 36216824, 2022).
nasopharyngeal carcinoma (5 papers, 2020 to 2025). A carcinoma arising from the nasopharyngeal epithelium. "Other targets involved in miR-135a-induced tumor suppression include IL-17 in nasopharyngeal carcinoma and homeobox A10 (HOXA10) in head and neck squamous cell carcinoma." (PMID 32944391, 2020). "Replication factor C subunit 4 (RFC4) facilitates the progression of nasopharyngeal carcinoma (NPC) through the modulation of HOXA10, which in turn promotes cellular proliferation and tumor growth." (PMID 40980067, 2025). "miR-873 and miR-129-5p down-regulate ZIC2, and HOXA10 can directly bind to the promoter of ZIC2 and up-regulate ZIC2 transcription in nasopharyngeal carcinoma 22-24." (PMID 37496990, 2023). "HOXA10 is downregulated by miR-320b; circ-CTDP1, which acts as a ceRNA for miR-320b, upregulates HOXA10 and, subsequently, promotes nasopharyngeal carcinoma progression through the upregulation of TGFB2." (PMID 34205978, 2021).
pancreatic cancer (5 papers, 2015 to 2025). "In PDAC, aberrant expression of several HOX transcription factors has been described and functional studies have shown that HOXA10, HOXB7, and HOXC11 promote pancreatic cancer development while HOXA1, HOXB1, and HOXB3 act as tumor-suppressors." (PMID 40619489, 2025). "Among the five top DEGs, overexpression of SERPINB5, HOXA10 and KRT16 at the mRNA level has previously been reported in pancreatic cancer." (PMID 28418924, 2017). "Previous studies indicated that HOXA10 and HOXA11 regulate expression of MMP-3 and MMP-2, respectively, and both MMPs contribute to migration/invasion of pancreatic cancer cells." (PMID 25912306, 2015). "It has previously been reported that some HOX genes are overexpressed in pancreatic tumors and they include HOXA10, HOXB7 and HOXB2, and transfection of Panc1 cells with siHOTTIP slightly decreased expression of HOXB7 but significantly decreased HOXA10 (>80%) and HOXB2 (>60%)." (PMID 25912306, 2015). "In pancreatic cancer cells, HOTTIP regulates HOXA10, HOXB2, HOXA11, HOXA9 and HOXA1, but not HOXA13." (PMID 30819158, 2019). "However, another study in pancreatic cancer cells demonstrated that HOTTIP did not modulate HOXA13 expression, but did regulate the expression of other HOX genes such as HOXA1, HOXA9, HOXA10, HOXA11 and HOXB2." (PMID 28938659, 2017).
cervical cancer (4 papers, 2017 to 2025). A primary or metastatic malignant neoplasm involving the cervix. "In our study, higher expression of PD‐L1 was observed in cervical cancer patients with low‐HOXA10 and HOXA11 expression." (PMID 34606634, 2021). "miR-149-5p was shown to be downregulated in HPV-positive cervical cancer, and HOXA10 has been shown to play a role in oral SCC impacting proliferation, migration, and invasion." (PMID 34638231, 2021). "The expression of HOXA1 was significantly upregulated in cervical cancer compared to normal control, whereas HOXA10 and HOXA11 were downregulated in cervical cancer." (PMID 34606634, 2021). "We also identified a significantly increased abundance of T helper 2 cells (Th2) and higher expression of PD‐L1 in cervical cancer patients with lower expression of HOXA10 and HOXA11." (PMID 34606634, 2021). "We observed significantly increased expression of several HOX cluster members, excepting HOXA10, among the cervical cancer cases, in comparison to the healthy controls." (PMID 28402266, 2017). "Subsequently, a significantly increased abundance of T helper 2 cells (Th2) and higher expression of PD‐L1 were observed in cervical cancer patients with lower expression of HOXA10 and HOXA11, indicative of the fact that HOXA10 and HOXA11 could be served as biomarkers of response to immunotherapy." (PMID 34606634, 2021). "Our results showed that among three differentially expressed HOXA genes (HOXA1, HOXA10, and HOXA11), HOXA1 was the only prognostic gene in cervical cancer." (PMID 34606634, 2021). "Our results showed that the HOXA1 gene was upregulated, while the HOXA10 and HOXA11 were downregulated in cervical cancer." (PMID 34606634, 2021). "Firstly, patients with cervical cancer were classified into two different group based on the cutoff value of HOXA1, HOXA10, and HOXA11 expression from ROC." (PMID 34606634, 2021). "In summary, this study represented the expression status of HOXA members in cervical cancer and identified three differentially expressed HOXA genes (HOXA1, HOXA10, and HOXA11) with great discriminative ability in cervical cancer." (PMID 34606634, 2021). "We identified three differentially expressed HOXA members in cervical cancer (upregulated HOXA1 and downregulated HOXA10 and HOXA11)." (PMID 34606634, 2021). "Firstly, we compared the expression of HOXA members in cervical cancer than normal controls, and results showed only three HOXA members with statistical significance (HOXA1, HOXA10, and HOXA11)." (PMID 34606634, 2021). "The expression profile of HOXA family was presented by pheatmap of R software, the result showing significant differences in HOXA1, HOXA10, and HOXA11 expression between cervical cancer and normal controls." (PMID 34606634, 2021). "Our results demonstrated that the expression of HOXA1 was upregulated in cervical cancer (p value for HOXA1 = 0.0128), while HOXA10 and HOXA11 expression was downregulated in cervical cancer compared with the normal control (p value for HOXA10 = 0.0123, p value for HOXA11 = 8.045E‐5)." (PMID 34606634, 2021). "Considering favorable efficacy in immune checkpoint inhibitors (especially PD‐1/PD‐L1 inhibitors) achieved in treating cervical cancer, our study also assessed the expression status of CTLA4, PD‐1, and PD‐L1 in cervical cancer patients grouped by different expression of HOXA1, HOXA10, and HOXA11." (PMID 34606634, 2021). "In our study, the decreased HOXA10 expression and increased HOXB13 expression were associated with reduced E-Cadherin and enhanced Vimentin expression, proposing the need for further studies to establish HOXA10 and HOXB13 as biomarkers of metastasis in cervical cancer." (PMID 28402266, 2017). "Thus the correlation plots of HOXA10 and HOXB13 with the EMT markers, suggest a role of HOXA10 and HOXB13 in driving metastasis in cervical cancer." (PMID 28402266, 2017).
cervical cancer (continued). "Pearson's correlation results showed that almost all assessed cg sites of HOXA1, HOXA10, and HOXA11 exhibited a negative correlation with expression in cervical cancer." (PMID 34606634, 2021).
colon cancer (4 papers, 2014 to 2025). "HOXA5, a paralog of HOXA10, has previously been reported to be down-regulated in colon cancer cells and its re-expression induces loss of the cancer stem cell phenotype, thereby preventing tumor progression and metastasis." (PMID 31763673, 2019). "It has been shown that the expression of PHGDH is regulated by many transcription factors, such as HOXA10, SMAD3 and ATF3, in endometrial endothelial cells, pulmonary epithelial cells and colon cancer cells." (PMID 39962071, 2025).
myoma (4 papers, 2013 to 2025). "The downregulation of PROKR2 suggests a possible disruption of the prokineticin signaling pathway, while the observed decrease in HOXA10 expression may be linked to myoma uteri and could influence fertility." (PMID 39915377, 2025). "Submucosal myomas cause a global decrease in HOXA10 and 11 expressions not only in the endometrial tissue over the fibroid but throughout the entire endometrial tissue, which suggests that the endometrium responds globally to a local myoma compression." (PMID 36430682, 2022). "In fact, a direct link was reported between myoma-derived transforming growth factor beta-3 and HOXA10 downregulation." (PMID 39274229, 2024). "This suggests that polyps may have a lesser effect on HOXA10 expression compared to myoma uteri." (PMID 39915377, 2025). "This study investigates the expression levels of HOXA10, PROKR1, PROK1, and related genes in endometrial tissues from patients diagnosed with EP and myoma uteri." (PMID 39915377, 2025). "In agreement with this study, both HOXA10 and HOXA11 genes expression were insignificantly increased in the endometrium after removal of myoma." (PMID 24639724, 2013). "The expressions of HOXA10 and HOXA11 were significantly decreased in the presence of submucosal myoma." (PMID 24639724, 2013). "It is shown that expressions of HOXA10 and HOXA11 were decreased in the presence of myoma." (PMID 24639724, 2013).
acute leukemia (3 papers, 2010 to 2025). A clonal (malignant) hematopoietic disorder with an acute onset, affecting the bone marrow and the peripheral blood. "HDODs also occupy a larger proportion of mixed phenotype acute leukemias (MPALs), express higher levels of HOXA10, and patients harboring HDODs have poorer OS (HR = 2.495, 95% CI: 1.147–5.426, p = 0.0394) in comparison to patients with LDODs." (PMID 41178390, 2025). "HOXA genes including HOXA10 represent key developmental regulators in myelopoiesis, and their deregulation plays a role in acute leukemias containing MLL-rearrangements and SET-NUP214 fusions." (PMID 35328612, 2022).
bladder cancer (3 papers, 2021 to 2025). "HOXA10 expression was significantly associated with the pathological grade and clinical stage of bladder cancer patients, thus suggesting that HOXA10 may be involved in the pathological progression of bladder cancer." (PMID 37627900, 2023). "HOXA10 protein expression was significantly higher in bladder cancer tissues as compared to adjacent normal tissues." (PMID 37627900, 2023). "Patients with high HOXA10 expression had lower survival rates as compared to those with low HOXA10 expression, thus suggesting that high HOXA10 expression is related to poorer bladder cancer prognosis." (PMID 37627900, 2023). "HOXA10 is overexpressed in bladder cancer tissues and contributes to the malignant behavior of bladder cancer cells." (PMID 37627900, 2023). "HOXA10 mRNA expression was found to be significantly upregulated in bladder cancer tissues and cell lines." (PMID 37627900, 2023). "The knockdown of HOXA10 in bladder cancer cells inhibited cell proliferation, migration, and invasion as well as decreased MMP3 expression." (PMID 37627900, 2023). "The high expression of HOXA10 promotes proliferation in bladder cancer, and it is also related to the low survival rate of bladder cancer patients." (PMID 33564686, 2021). "The knockdown of HOXA10 inhibited cell migration and invasion in bladder cancer in vitro." (PMID 37627900, 2023). "In bladder cancer, HOXA10 may accelerate metastasis by regulating FOSL1 expression." (PMID 39790460, 2025). "In addition, HOXA10 promoted the metastasis of bladder cancer by regulating FOSLI." (PMID 37627900, 2023). "Hence, HOXA10 may be a potential biomarker for evaluating the progression of bladder cancer and a potential therapeutic target for bladder cancer." (PMID 37627900, 2023).
chronic endometritis (3 papers, 2024 to 2025). A non-granulomatous or granulomatous chronic inflammation of the endometrium. "Therefore, in this study we attempted to demonstrate a possibleimpact of chronic endometritis on the expression of HOXA10 and HOXA11 in infertilewomen." (PMID 38801313, 2024).
cryptorchidism (3 papers, 2018 to 2025). The failure of one or both testes of a male fetus to descend from the abdomen into the scrotum during the late part of pregnancy. "Knocking out HOXA10 in male mice caused cryptorchidism, and a similar HOXA10 deletion was found in a sample of patients with cryptorchidism, albeit in a very small sample." (PMID 34367069, 2021). "For example, in the mouse cryptorchidism model, the expression of testicular descent-related genes insulin-like peptide 3 (INSL3) and homeobox protein Hox-A10 (Hoxa10) was significantly reduced." (PMID 41217791, 2025).
female infertility (3 papers, 2021 to 2025). Diminished or absent ability of a female to achieve conception. "Like HOXA10, HOXA11 expression plays animportant role in implantation and the down regulationof this gene leads to female infertility." (PMID 32347039, 2021).
hyperandrogenism (3 papers, 2017 to 2023). Excessive secretion of androgens from the adrenal glands or gonads. "Women with PCOS may be associated with hyperandrogenism, which may consequently induce aberrant expression of both AR and HOXA10 in the endometrium." (PMID 34053455, 2021). "Hyperandrogenism could affect the window of implantation by decreasing the expression levels of HOXA10 and WT1 genes and influencing endometrial decidualization." (PMID 38033994, 2023). "As opposed to our findings, patients with hyperandrogenism secondary to Polycystic Ovarian syndrome (PCOS) demonstrated low HOXA-10 and β3-integrin expression, suggesting androgens may have a detrimental impact on the endometrium." (PMID 29278227, 2017).
Insulin resistance (3 papers, 2021 to 2026). Increased resistance towards insulin, that is, diminished effectiveness of insulin in reducing blood glucose levels. "Enhancements in inflammatory and metabolic indicators, such as decreased TNF-α, IL-6, and insulin resistance, may facilitate ideal endometrial gene expression profiles associated with implantation, including integrins, HOXA10, IGFBP-1, and angiogenic pathways." (PMID 41596408, 2026). "Additionally, the mechanism by which metformin upregulates the expression of HOXA10 in the endometrium of women with PCOS may be mediated through improvement in peripheral insulin resistance." (PMID 34053455, 2021).
atherosclerosis (2 papers, 2013 to 2020). A disease characterized by the build-up of fatty material and calcium deposition in the arterial wall resulting in partial or complete occlusion of the arterial lumen. "For example, HoxA9, HoxA10, and HoxD3 were expressed at higher levels in EC isolated from iliac arteries that are relatively protected from atherosclerosis compared to coronary arteries that are atherosusceptible." (PMID 31504243, 2020). "In this network, smoking was directly connected to 2 genes, CYP1B1 and HOXA10, which both have relevance to atherosclerosis and smoking." (PMID 23372645, 2013).
chordoma (2 papers, 2017 to 2023). Chordomas are rare malignant tumors arising from embryonic remnants of the notochord in axial skeleton. "Comparison of chordoma with NP showed DMRs in many cancer-related genes as well as in genomic cluster encoding homeobox domain genes (at HOXD3, HOXD4 and HOX11, HOXA9, HOXA10) that play an important role in both normal differentiation and tumorigenesis." (PMID 37434245, 2023). "We further analysed the in situ protein expression of HOXA10 in the 24 sacral and five clivus chordoma patients from our chordoma tissue bank by immunohistochemistry." (PMID 28515451, 2017). "A strong nuclear positivity (+++) was detected in the majority of tumour cells in 20/24 sacral chordoma cases whereas the clivus cases had low levels of HOXA10 or were completely negative." (PMID 28515451, 2017). "Immunohistologically, clivus chordomas had no or very low levels of HOXA10 protein while sacral chordomas showed a strong nuclear positivity in all samples analysed." (PMID 28515451, 2017).
endometrial adenocarcinoma (2 papers, 2014 to 2018). "β3 integrin mRNA levels are increased in endometrial adenocarcinoma cells transfected with a HOXA10 expression vector and are decreased in the cells treated with a HOXA10 antisense construct." (PMID 25136598, 2014).
gastric tumor (2 papers, 2021 to 2023). "Hypomethylation of HOXA10 is associated with higher levels of HOXA10 and miR-196b-5p in GC; the reconstitution of the TFF1, which acts as gastric tumor suppressor, induces methylation of HOXA10, thereby leading to decreased levels of HOXA10 and miR-196b-5p." (PMID 37239435, 2023). "The expression levels of HOXA10 were negatively correlated with the invasion ability of gastric tumor cells." (PMID 34925694, 2021).
meningioma (2 papers, 2013 to 2015). A generally slow growing tumor attached to the dura mater. "Similar to TIMP3, repression of HOXA7, HOXA9, and HOXA10 in meningioma is also associated with clinically aggressive behaviour." (PMID 26101774, 2015). "DNA methylation levels of HOXA7, HOXA9, and HOXA10 were reported to be significantly higher in atypical and anaplastic meningiomas than in the benign form." (PMID 26101774, 2015). "DNA methylation levels of HOXA7, HOXA9 and HOXA10 were reported significantly higher in WHO grade II and III meningiomas than in grade I (benign) meningiomas." (PMID 23349797, 2013).